APOE (apolipoprotein E)
Diseases named in the same sentence as APOE in open-access papers (continued):
Sharing a sentence is not in itself a finding about the gene and the disease.
atherosclerosis (continued). "Compared with the mice in the ApoE−/− + HFD + AAV-NC group, a significant increase in Oil Red O positive area and arterial plaque area was observed in the ApoE−/− mice injected with STZ (ApoE−/− + HFD + STZ + AAV-NC), highlighting the exacerbating effect of diabetes on atherosclerosis." (PMID 40337510, 2025). "Interestingly, despite a lack of overt atherosclerosis, young ApoE-/- mice demonstrate increased levels of LDL-cholesterol and serum triglycerides that do not change following MHV68 infection (data not shown)." (PMID 40439406, 2025). "Hence, altered systemic metabolism did not appear to explain altered atherosclerosis in hIGFREO/ApoE−/−." (PMID 40171617, 2025). "Even in non-diabetic apoE-deficient mice, sRAGE administration reduces plaque burden, albeit to a lesser extent than in diabetic models, underscoring the role of AGE–RAGE signaling in both diabetes-accelerated and basal atherosclerosis." (PMID 40806443, 2025). "ApoE−/− mice are genetically engineered mouse models lacking the ApoE protein, which is essential for lipid metabolism, and they spontaneously develop hypercholesterolemia and atherosclerosis, making them a valuable tool for studying CVD and cholesterol-related disorders." (PMID 39796594, 2024). "In the current study, we were interested in elucidating the effects of arterial endothelial inflammation on the aorta in the absence of a deregulated lipoprotein and cholesterol balance—thus, on an ApoE wild-type background and under normal diet—and, therefore, in the absence of atherosclerosis." (PMID 38727309, 2024). "In models of experimental atherosclerosis, B2 cell depletion achieved through the antibody-mediated blocking of the BAFF receptor has resulted in decreased B cell zones in the spleen of hyperlipidemic ApoE-/- mice while limiting the progression of atherosclerotic plaques." (PMID 38686373, 2024). "However, it is important to note that mild hyperlipidemia on a normal diet does not induce atherosclerosis in apoE KO rabbits." (PMID 39087075, 2024). "In addition, the use of Apoe−/− mice may interfere with studies on TREM2, as APOE is a known downstream effector of TREM2.Here, we summarize the mouse models used in current atherosclerosis research and their respective findings for reference." (PMID 39497214, 2024). "We employed an ApoE-/- gene knockout mouse model and subjected them to a high-fat diet, followed by FMN intervention, to comprehensively investigate the mechanistic role of FMN in countering atherosclerosis and its potential applications in the therapeutic management of atherosclerosis." (PMID 38388385, 2024). "The evaluation of aortic morphology in ApoE-/-mice revealed that FMN significantly improved the plaque area, fibrous cap protrusion, lipid deposition, and structural alterations on the aortic surface, among other markers of atherosclerosis,and there is concentration dependence." (PMID 38388385, 2024). "Second, to investigate whether NETosis participates in atherosclerosis, NETs were observed abundantly within atherosclerotic lesions of aortic roots in mice lacking ApoE (ApoE-/-) who were nurtured with high-fat diets (HFD) for 8 continuous weeks." (PMID 36851139, 2023).
atherosclerosis (continued). "However, the ApoE mouse model is costly and although the general belief is that normal, wild type mice are not suitable for the study of atherogenesis and atherosclerosis, this has not been substantiated in the literature." (PMID 38151517, 2023). "Furthermore, 160 ApoE–/– Ang II AAA-stage-specific cytokines and chemokines have also been identified at Ang II infusion for 7 days, 14 days, and 28 days, and 94 atherosclerosis stage-specific cytokines and chemokines have been identified at HFD feeding for 6 weeks, 32 weeks, and 78 weeks." (PMID 38327764, 2023). "In APOE−/− mice, PGC-1α deficiency did not contribute to enhanced atherosclerosis." (PMID 37175915, 2023). "Finally, the same double ApoE model but fed with a high-cholesterol “western” diet showed reduced atherosclerosis in the absence of Gal-3." (PMID 38170009, 2023). "This may be why we observed a sex-specific increase in atherosclerosis in female, but not male, ApoE−/− mice." (PMID 37064902, 2023). "This study aimed to investigate whether ophthalmic artery reactivity is affected in mice lacking the apolipoprotein E gene (ApoE−/−), a model for hypercholesterolemia and atherosclerosis." (PMID 37873768, 2023). "Importantly, CETP expression in apoE−/− mice did not enhance atherosclerosis by increasing circulating SAA, since SAA levels were generally lower, not higher, in mice administered AAV-CETP." (PMID 37004910, 2023). "We found that chronic LD shifts exacerbated atherosclerosis in female, but not male, ApoE−/− mice." (PMID 37064902, 2023). "Mice lacking both eNOS and ApoE display increased blood pressure when compared to ApoE-null mice, suggesting that accelerated atherosclerosis may be due to systemic hypertension." (PMID 38034389, 2023). "However, the expression of CETP did not affect atherosclerosis in apoE−/− SAA-TKO mice (6.2 ± 0.9% compared with 5.1 ± 1.1% in the presence and absence of CETP expression, respectively, P = NS), and the interaction was significant (P = 0.043)." (PMID 37004910, 2023). "While unexpected, it is potentially related to the hyperlipidemic nature of these atherosclerotic models and alterations to classical LDL clearance, which is consistent with statins typically not yielding robust reductions in atherosclerosis or serum LDL in the ApoE−/− mouse model." (PMID 38026185, 2023). "Furthermore, we found that the effect of quercetin on atherosclerosisrequired gut microbes, as supplementation of this flavonoid to germ-free (GF)ApoE KO mice consuming the high-MAC diet did not affect thedevelopment of atherosclerosis." (PMID 36712088, 2023). "Indeed, the PPARγ agonist pioglitazone and PPARα fenofibrate reduced atherosclerosis and hepatic steatosis in mice lacking both ApoE and Farnesoid x receptor (FXR), which modeled NASH and atherosclerosis simultaneously." (PMID 37200978, 2023). "Likewise, treatment with tetrahydrobiopterin improved endothelial cell function and improved atherosclerosis in ApoE-/- mice independent of plasma cholesterols." (PMID 37163513, 2023). "Without altering circulating total cholesterol, triglycerides or HDL, or lipid profile, the provision of exogenous 27HC increased early plaque formation and early atherosclerosis progression in apoE−/− mice expressing endothelial ERα, but not in apoE-/- lacking endothelial ERα." (PMID 37491347, 2023). "Nevertheless, among five proteins that differ between individuals with coronary artery disease and control subjects, ApoE was found to be the most prevalent protein in HDL obtained from atherosclerotic lesions, indicating its potential significance in the pathophysiology of atherosclerosis." (PMID 37242746, 2023).
atherosclerosis (continued). "The downregulation of miR-378a-3p in hyperlipidemic ApoE−/− mouse aortic macrophages results in a reduction of signal regulatory protein (SIRP) α and hinders the clearance of apoptotic cells within plaque lesions, accelerating the progression of atherosclerosis." (PMID 37259293, 2023). "No change in atherosclerosis was observed in ApoE−/−CD8−/− mice." (PMID 37681883, 2023). "The reduction of IP angiogenesis in ApoE−/−PFKFB3ECKO mice, as described in this study, is also in line with previous findings in our group showing decreased IP angiogenesis following administration of the glycolysis inhibitor 3PO in a mouse model of advanced atherosclerosis." (PMID 34432198, 2022). "It is observed that, in comparison with the control group, the endothelium of apoE-/- mice with S1 or S3 treatment showed less TUNEL positive area and decreased ICAM-1 and VCAM-1 protein level, suggesting S1 and S3 inhibited endothelium injury during atherosclerosis development." (PMID 35335352, 2022). "The implication of the upstream classical pathway independent of terminal pathway activation is unclear, and over activation of the classical pathway in absence of ApoE might counterbalance the beneficial effect of a C5 knockout on atherosclerosis." (PMID 36142647, 2022). "Additionally, in apolipoprotein E knockout mice, TNF-α suppression lowers atherosclerosis." (PMID 36422550, 2022). "In contrast, pharmacological inhibition of RIPK1 kinase with GSK’547 (10 mg/kg BW/day) in ApoE−/− Fbn1C1039G+/− mice, a model of advanced atherosclerosis, did not alter plaque size after 20 weeks WD, but induced apoptosis (TUNEL: 136 ± 20 vs. 62 ± 9 cells/mm2, p = 0.004)." (PMID 35625752, 2022). "However, another TCRδ-/-ApoE-/- mouse study found no critical role for γδ T cells in the development of early atherosclerosis in the total aorta of mice after 10 weeks of high-fat diet feeding." (PMID 35874761, 2022). "In addition, apolipoprotein E (ApoE) is an endogenous inhibitor of collagen type VIII, which may explain why ApoE−/− mice develop atherosclerosis." (PMID 36430208, 2022). "ApoE−/− mice aged 8 weeks and fed an HFD (high-fat diet) for 4 months were used to establish atherosclerosis animal models and had significantly elevated blood lipid indicators and blood vessel wall thickening, indicating that we have successfully constructed an atherosclerosis model." (PMID 35631669, 2022). "In this research, we applied ApoE−/− mice to establish a model of SLE combined with atherosclerosis by intraperitoneal injection of pristane, and evaluated the effects of QB, Qinghao, Biejia, and a representative western drug, HCQ, on SLE combined with atherosclerosis." (PMID 35571092, 2022). "Therefore, ApoE-/- mice were infected with endothelial-specific RGDKRVS-AAV9-shSRC-3 or control shRNA virus by tail vein injection before being fed a WD, and a model of atherosclerosis was constructed." (PMID 36263184, 2022). "However, study on the effects of IL-27/anti-IL-27 antibody (anti-IL-27p28-Ab) administration to atherosclerosis model in ApoE−/− mice has not been reported." (PMID 36405994, 2022). "In addition, RAGE gene knockout protected against the development of atherosclerosis in both diabetic and nondiabetic ApoE-null mice." (PMID 35370631, 2022).
atherosclerosis (continued). "In addition, apolipoprotein E (APOE)/Cxcl10/mice fed with a Western-style diet for either 6 or 12 weeks demonstrated a significant atherogenesis inhibition compared with APOE (−/−) controls, revealing the role of CXCL10 in atherosclerosis progression." (PMID 34835155, 2021). "In atherosclerosis, even though curcumin-induced IL-10 has not been explored previously, atheroprotective effects of high dose oral curcumin were related to Th2/Treg balance modulation in asthmatic ApoE-/- mice." (PMID 34305950, 2021). "We speculate that this may reflect the influence of factors other than estrogens in eADA control in ApoE-/-LDL-R-/- mice, for example, in the appearance of an inflammatory state during development of atherosclerosis, which may influence the interaction of estradiol with the purinergic system." (PMID 32935303, 2021). "Therefore, one-month old female apoE KO mice were fed standard chow (control; Con) or adenine (Ade) diets with or without iodomethylcholine (IMC) for 14 weeks to examine the effects of reduced TMAO on CKD and atherosclerosis." (PMID 33436815, 2021). "Furthermore, ApoE−/− mice treated with GB significantly inhibited the mRNA level and protein expression of FMO3, and then decreased the concentration of TMA and TMAO, thus slowing down the progression of atherosclerosis." (PMID 34888358, 2021). "Moreover, Tlr4 expression is higher in macrophages in atherosclerotic plaques of ApoE−/− mice on an atherogenic diet and in humans, suggesting that TLR4 represents a pathophysiological link between oxidized lipids, inflammation, and atherosclerosis." (PMID 35083304, 2021). "Concomitant treatment of cholesterol-fed ApoE−/− mice with LT, the specific synthetic Rac1 inhibitor NSC 23766 or simvastatin comparably reduced aortic Rac1 activity, NADPH oxidase activity, oxidative stress, endothelial dysfunction, atherosclerosis development, and macrophage infiltration." (PMID 34422919, 2021). "Atherosclerosis-prone apolipoprotein E-null (Apoe−/−) mice placed on a high cholesterol high fat diet (HCD; 0.2% cholesterol; 60% kcal of fat) for 16 weeks showed a significant increase in serum Dj-1 levels compared to Apoe−/− mice on normal chow diet (NCD) (0.02% cholesterol; 17% kcal of fat)." (PMID 33633277, 2021). "In the ApoE–/– mouse model, results showed sensitive and specific detection of CCR5 in plaques not only along the progression of atherosclerotic lesions, but also during plaque regression and the human ex vivo experiment, which confirmed the potential of CCR5 targeting in human atherosclerosis." (PMID 34885690, 2021). "GAS5 overexpression in apoE−/− mice with atherosclerosis also increased total cholesterol (TC), free cholesterol (FC), cholesterol ester (CE), low-density lipoprotein (LDL) levels, aortic plaque, and lipid accumulation; however, silencing of GAS5 prevented the progression of atherosclerosis." (PMID 34179148, 2021). "To test this hypothesis, we generated dysferlin-null mice lacking apolipoprotein E (ApoE), a common model of atherosclerosis, dyslipidemia and endothelial injury when stressed with a high fat, and cholesterol-rich diet." (PMID 34366880, 2021). "However, another study showed that atherosclerosis in ApoE−/− mice is not dependent on the NLRP3 inflammasome." (PMID 33535473, 2021).
atherosclerosis (continued). "ApoE KO mice, instead of wild-type mice, were chosen for this study since we aimed to study atherosclerosis and these mice develop hypercholesterolemia and atherosclerosis spontaneously without dietary intervention." (PMID 33436815, 2021). "Although rampant atherosclerosis in the arteries from ApoE-/- mice did not appear to alter B cell populations from spleen or peritoneum, it may affect B cells at the site of inflammation." (PMID 34305930, 2021). "In vivo results using ApoE-/- mice showed that GATA6 is overexpressed in the endothelium of atherosclerosis-susceptible region (OS region) of the cardiovascular system, but not in the endothelium of atherosclerosis-resistant region (PS region)." (PMID 34336268, 2021). "Continual infusion of the vasoactive peptide angiotensin II, associated in the previous experiments with vascular remodeling and atherosclerosis, lead to the development of aneurysms in the suprarenal abdominal aorta in apolipoprotein E knock out (ApoE-/-) mice without affecting the thoracic aorta." (PMID 32878347, 2020). "Our data demonstrate a more profound effect of shifts in LD cycle on the circadian timing system of female mice, which could explain why that intervention, rather than constant light, aggravates atherosclerosis in female APOE*3-Leiden.CETP mice." (PMID 32915671, 2020). "Since mouse immune responses and pathways are similar to those of humans, they are a good model for studying atherosclerosis-related inflammatory responses, whereas the HDL-based lipid metabolism and the lack of CETP in mice are clear disadvantages, that are only abolished in ApoE*3-Leiden.CETP." (PMID 32714944, 2020). "However, the knockout of ST2 or IL-33 showed no beneficial effect on atherosclerosis development in ApoE−/− mice." (PMID 33415128, 2020). "An additional strength of our study is that we studied both male and female ApoE−/− mice, while only females could be studied in the previous study because male APOE*3 Leiden.CETP mice do not develop atherosclerosis on a cholesterol-rich diet." (PMID 32555251, 2020). "Indeed, we found that the expression of LOC285194 was substantially lower in atherosclerotic plaques of ApoE-/- mice (0.7 ± 0.2) when compared with that of wild type control mice(4.5 ± 1.3), suggesting that LOC285194 may play a role in atherosclerosis." (PMID 31884873, 2020). "In a study in which the effect of excess SAH in ApoE−/− mice was explored in the absence of excess Hcy, plasma SAH was positively associated with increased atherosclerosis and negatively associated with the content of trimethylated histone H3 on lysine 9 in aortic lesions." (PMID 32717800, 2020). "ApoE−/−FBXW2fl/flLysmCre+/− mice exhibited smaller lesions with fewer CD68+ plaque areas, suggesting that FBXW2 deletion in macrophages may alleviate progression of atherosclerosis in mice." (PMID 33101872, 2020). "Besides, an olive extract rich in secoiridoids has shown its capacity to weaken initial steps of atherosclerosis due to significant reduction of endothelial dysfunction biomarkers such as E-selectin, VCAM-1, MCP-1, ICAM-1 and F4/80 in ApoE−/− mice, an atherosclerosis-prone mouse model." (PMID 33322700, 2020).